PLAUR (plasminogen activator, urokinase receptor)
Diseases named in the same sentence as PLAUR in open-access papers (continued):
Sharing a sentence is not in itself a finding about the gene and the disease.
tumor (continued). "The mRNA expressions of PLAU and PLAUR varied remarkably among different ages, tumor histology, WHO grades and tumor types, IDH-1 mutation, and 1p19q status and other clinical characteristics." (PMID 35087738, 2021). "PLAUR has been found to have a key role in tumor cell motility, invasion, metastasis, EMT, cancer stemness, survival, and treatment resistance in recent research." (PMID 34950596, 2021). "Accordingly, elevated levels of PLAUR were observed in tumor tissues when compared with their paired non-tumor mucosa." (PMID 29075357, 2017). "As previously reported, PLAUR protein is expressed in both tumor cells and peritumoral stroma (70 out of 96, 73% positive)." (PMID 14737219, 2004). "Understanding the interactions between these molecules could aid in the design of targeted therapies for specific patient populations and in the development of new drugs to modulate PLAUR expression or its function in tumor development." (PMID 40561678, 2025). "For instance, knockdown or overexpression experiments of SNHG14, hsa-miR-340-5p, and PLAUR in NSCLC cell lines could elucidate their regulatory roles in tumor progression and immune cell infiltration." (PMID 40561678, 2025). "Targeting the ncRNAs involved in this axis, such as AC008555.6, AC026356.1, TRHDE-AS1, or SNHG14, could potentially disrupt the regulatory mechanisms that lead to PLAUR overexpression, thereby reducing tumor progression and improving patient outcomes." (PMID 40561678, 2025). "This study provides insights into the molecular mechanism of action of PLAUR in NSCLC, which may help to develop new drugs to regulate PLAUR expression or its function in tumor development and provide new targets for the treatment of NSCLC." (PMID 40561678, 2025). "The results of this study suggest that PLAUR may influence the progression of NSCLC mediated by tumor immune infiltration." (PMID 40561678, 2025). "Second, the inhibition of PLAUR could disrupt the tumor microenvironment, leading to increased immune cell infiltration and enhanced antitumor immunity." (PMID 40561678, 2025). "The present results indicate that the presence of PLAUR in tumors could contribute to the development of oncogenic functions through the infiltration of tumor immune cells and the expression of immune checkpoints." (PMID 40561678, 2025). "•Significant differences in the expression of PLAUR in NSCLC tumor types." (PMID 40561678, 2025). "The current study also suggested that PLAUR could exert its tumourigenic effects by regulating tumor immune cell infiltration and immunomodulatory function." (PMID 40561678, 2025). "•PLAUR-mediated carcinogenesis of NSCLC involves tumor immune escape." (PMID 40561678, 2025). "Our findings supported that PLAU overexpressed in tumor tissue could interact with PLAUR to regulate the crosstalk between malignant epithelial cells and immune cells, presumably favoring immune escape in HNSCC." (PMID 39511134, 2024). "PLAU overexpressed in tumor epithelia could increase its binding with the receptor PLAUR, expressed mainly on macrophages, to ultimately influence the aberrant epithelial–immune interactome in HNSCC." (PMID 39511134, 2024). "Moreover, the overexpression of PLAU in tumor epithelial cells facilitates its interaction with the receptor PLAUR, predominantly expressed on macrophages, thereby influencing the abnormal epithelial–immune interactome in HNSCC." (PMID 39511134, 2024). "We found that most TAMs and some tumor cells expressed PLAUR." (PMID 38398231, 2024). "These KACs had increased expression of CDKN1A, CDKN2A, PLAUR and the tumour marker CLDN4." (PMID 38418883, 2024). "EMT, which is closely related to the invasiveness of tumor cells, can also be regulated by PLAUR." (PMID 38398231, 2024). "Using a protein network analysis, we speculate that PLAUR activates immune cells and assists their migration/adhesion to the inflammatory sites, and promotes tumor cell migration, mainly through ECM remodeling." (PMID 38396677, 2024).
tumor (continued). "PLAUR may be involved in tumor immunity and leads to tumor invasion and metastasis by regulating extracellular matrix degradation and tissue remodeling." (PMID 37153595, 2023). "In addition, some studies have indicated that tumoral and macrophage PLAUR can promote tumor invasiveness and that macrophages can increase the expression of PLAUR in tumor cells." (PMID 37153595, 2023). "Hypoxia increases the tumor cells invasion by upregulating PLAUR expression." (PMID 37237021, 2023). "In addition, some studies have used PLAUR as a tumor immune-related gene to construct prognostic models." (PMID 35675366, 2022). "Studies have also shown that abnormal expression of PLAUR in tumors could cause an increase in tumor macrophage infiltration, and these results suggest that PLAUR function may be related to tumor immunity." (PMID 35675366, 2022). "To further confirm our in vitro observations, we explored whether PLAUR regulates the growth and metastasis of tumor cells in vivo." (PMID 35864968, 2022). "IHC analysis revealed that PLAUR knockdown inhibited the expression of Ki67 in tumor tissues." (PMID 35864968, 2022). "The PLAUR gene is a key gene involved in coagulation and fibrinolysis, which are under complex regulation by inflammation and the local recruitment of leukocytes in the tumor microenvironment." (PMID 36052236, 2022). "The protein encoded by the PLAUR gene is the receptor of PLAU (plasminogen activator, urokinase), which plays a momentous role in the migration and proliferation of tumor cells through remodeling of the extracellular matrix and the tumor microenvironment." (PMID 35222525, 2022). "In addition, our study also found that there was a significant correlation between high PLAUR expression and tumor stage and grade." (PMID 35675366, 2022). "Therefore, it is clinically useful to investigate further the relationship between PLAUR expression and tumor immune infiltration in KIRC." (PMID 36052236, 2022). "As expected, PLAUR knockdown significantly delayed in vivo tumor growth in nude mice." (PMID 35864968, 2022). "The membrane-bound receptor PLAUR activates a cascade of extracellular proteinases with functions in tissue remodeling upon binding of its ligand, urokinase-type plasminogen activator (UPA), and upregulation of PLAUR promotes survival, migration and metastasis of tumor cells in vitro." (PMID 33690729, 2021). "Interestingly, the PLAUR gene expression in tumor tissues showed a statistically significant increase in ~48% (15 out of the 31) of the cancer types tested, while a substantial downregulation was detected in only ~6% (2 out of 31)." (PMID 32337090, 2020). "Based on our IHC results, we propose that the effects of PLAUR mRNA expression on patient survival may reflect the activity of the small sub-population of uPAR-immunopositive cells in the tumor." (PMID 29445239, 2018). "Genetic knockdown of PLAUR has demonstrated strong anti-tumor activity." (PMID 29254187, 2017). "It has been proposed that amplification of a single chromosomal region (for example, HER2) may destabilize the tumor genome, thereby facilitating the amplification of an additional loci (for example, PLAUR)." (PMID 25897424, 2015). "Plasminogen activator, urokinase receptor (uPAR) constituting a part of uPA-PAI extracellular matrix degradation system might facilitating tumor cells invasion, migration and growth." (PMID 24709997, 2014). "Additionally, abnormal PLAUR expression in tumors has been shown to increase tumor macrophage infiltration, suggesting that there may be a relationship between PLAUR function and tumor immunity." (PMID 40561678, 2025). "Collectively, these data suggest that the overexpressed PLAU in tumor epithelia could interact with its receptor PLAUR located on the surface of immune cells (especially macrophages), to influence the interaction mode of aberrant epithelial cells and immune cells in HNSCC." (PMID 39511134, 2024).
tumor (continued). "Thus, PLAUR is also involved in the Tumor Microenvironment pathway." (PMID 37513116, 2023). "The results of the analysis of correlation between PLAUR expression and sensitivity to commonly used chemotherapeutic agents (cisplatin, gemcitabine, paclitaxel, sorafenib, sunitinib and pazopanib) showed that high PLAUR expression increased tumor sensitivity (P < 0.05)." (PMID 35675366, 2022). "Interestingly, four genes (TIMP1, SERPINE1, PLAUR and PTX3) associated with poor overall survival of both LUAD and LUSC patients, are involved in the regulation of ECM remodelling, which plays a key role in the aggravation of tumour malignancy and metastasis." (PMID 34807957, 2021). "PLAUR could be functionally related to tumor growth and angiogenesis." (PMID 32021566, 2020). "Finally, the effects of PLAUR mRNA expression on patient survival in a tumor type in which only a small sub-population of the cells express uPAR protein raises the question of whether one cancer cell in a malignancy can make adjacent cells more aggressive." (PMID 29445239, 2018). "Cell Adhesion and Migration: CD44, ITGB1, LAMB1, FAT1, PLAUR, and TGFBI are integral to cell–matrix interactions and extracellular matrix (ECM) remodeling, processes critical for tumor invasion and metastasis." (PMID 41303451, 2025). "PLAU and its receptor PLAUR have been shown to induce a mesenchymal gene expression signature in GBM cells, promoting tumor cell survival and correlating with poor prognosis." (PMID 40835683, 2025). "Inter-tumor Core and Rim regions showed significantly higher relative expression of hypoxia response genes, including LDHA, VEGFA, LOX, PLAUR, SERPINE1, and IGFBP3." (PMID 37434262, 2023). "The results showed that the expression patterns of SPP1 and CSF1 in normal and tumor tissues were most similar to those of ITGAV and PLAUR, respectively." (PMID 37097499, 2023). "For example, in TAMs, gene expression of FPR3, PLAUR, and LRP1, the receptor genes interacting with tumor cells, was correlated with ligand genes interacting with CD8+ T cells including C5AR1." (PMID 38002057, 2023). "As expected, ITGA5, PLAU, PLAUR, SERPINE1, TGFB1, and VEGFC were consistently overexpressed in tumor tissues compared to normal tissues (log2FC > |1| and p ≤ 0.01)." (PMID 36425786, 2022). "Analysis of the five hypoxia- and immune-related genes also showed high expression of EPO, TGFB1, TGFA, and PLAUR, but low expression of TEK in tumor samples." (PMID 35222525, 2022). "PLAUR, which is also known as CD87, UPAR, URKR, and U-PAR, is found to be overexpressed in multiple cancers including GBM, and contributes to tumor angiogenesis, cell migration, and invasion." (PMID 35372355, 2022). "The plasminogen activator urokinase receptor (PLAUR) plays key roles in tissue remodeling and extracellular matrix degradation, which contribute to invasion and metastasis, a major feature of tumor malignancy." (PMID 35675366, 2022). "We also obtained tumor staging data from GSE53757 and found that PLAUR expression was positively correlated with ccRCC progression." (PMID 35675366, 2022). "The expression of LINC00460/EME1/HNRNPAB/PLAUR and SEMA3A was higher in most tumour tissues, including LUAD, than in the corresponding control tissues (P < 0.001)." (PMID 36091160, 2022). "Two previous studies indicated that PLAUR expression was upregulated in KIRC tissues compared to normal tissues, and the expression appeared to increase with tumor grade or stage." (PMID 36052236, 2022). "The relationship between the abundance of tumour-infiltrating lymphocytes (TILs) and the expression of EME1/HNRNPAB/PLAUR/SEMA3A in pan-cancer and LUAD was demonstrated on heatmaps and lollipop graphs." (PMID 36091160, 2022). "Of these genes, ITGA5, PLAU, PLAUR, SERPINE1, TGFB1, and VEGFC were significantly highly expressed in tumor compared to normal tissues." (PMID 36425786, 2022).
tumor (continued). "PLAUR, PABPC1L, SLC16A12, NFE2L3, and KCNAB1 presented significantly different expression levels between tumor tissues and normal tissues." (PMID 35211477, 2021). "Except for some inflammation-related signaling pathways, several tumor-related signaling pathways have a relationship with PLAU and PLAUR co-expression networks." (PMID 35087738, 2021). "LY6D, LY6E, PLAUR, PSCA, CD59 and LYPD3 mRNA expression was significantly increased in the PDAC tumor tissues than normal adjacent tissues (p < 0.01)." (PMID 33613843, 2021). "In the tumor samples, F2, GLS2, IDO2, and PLAUR were shown to be significantly upregulated, while GNG7, PIK3CG, and ST3GAL6 were significantly down-regulated." (PMID 33619235, 2021). "Searching for predicted and validated miR-335 target genes, we found that PLAUR (p = 0.046) and CDH11 (p = 0.049) are potential targets which participate in metastasis and tumor invasion pathway." (PMID 29075357, 2017). "In addition, we also found that the expression of PLAUR was positively correlated with MHC I, MHC II, and immune functional programs in the MES-like tumor cells." (PMID 38398231, 2024). "Therefore, the present study suggests that NCAPD3-knockdown-induced differentially expressed genes (DEGs) such as CRNDE, EDN1, and JUNB can regulate cell and tumor invasion through EGFR and PLAUR." (PMID 38711992, 2024). "Taken together, these results suggest that PLAUR could determine the MES phenotype of GBM as a tumor cell-intrinsic gene and support tumor progression in vivo." (PMID 38398231, 2024). "Cluster 2 may consist of pro-tumor macrophages with the specific expression of MARCO and PLAUR (expressing e.g., CTSL, MARCO and PLAUR) and the proportion was significantly increased compared with N group." (PMID 37153595, 2023). "As cancer malignancy progresses, the urokinase-type plasminogen activator receptor (uPAR or PLAUR) plays a key role, as it is not expressed in normal tissues but is strongly expressed in tumor tissues." (PMID 35864968, 2022). "Although the results of the correlation analysis of PLAUR methylation and stage and T stage were not significant, a trend of negative correlation between PLAUR methylation with tumor progression was also observed." (PMID 35675366, 2022). "Therefore, these six tumor-related genes (ITGA5, PLAU, PLAUR, SERPINE1, TGFB1, and VEGFC) were considered as prognostic biomarkers for HNSCC." (PMID 36425786, 2022). "Furthermore, we analyzed the expression of ceRNAs in tumour and control samples using TCGA, GTEx, and CPTAC databases and found that the expressions of LINC00460/EME1/HNRNPAB/PLAUR/SEMA3A were significantly higher in LUAD tissues." (PMID 36091160, 2022). "In addition to the abnormal expression during tumor progression, PLAU and PLAUR are also found involved in complicated tumor invasion and cell migration." (PMID 35087738, 2021). "Additionally, genes involved in extracellular matrix remodelling and adhesion, such as PLAUR, PLG and CEACAM4, may enhance tumour invasion by modifying the tumour microenvironment, a process extensively reported in invasive malignancies." (PMID 40830065, 2025). "IFNGR2, KLF10, PLAUR, MSN, and IKBIP, whose coefficients of risk score were >0, had positive correlations with risk score, stromal score, immune score, and ESTIMATE score and negative relationships with tumor purity." (PMID 38137116, 2023). "Gene expression difference analysis manifested that NCF2 was differentially expressed in normal and tumor tissue, rather than ITGB6 and PLAUR." (PMID 36680322, 2023). "In contrast, the PLAUR and TGFB1 proteins were expressed in tumor cells, but only at a very weak level (data not shown)." (PMID 36425786, 2022).
cancer (447 papers, 1997 to 2026). A tumor composed of atypical neoplastic, often pleomorphic cells that invade other tissues. "High expression of PLAUR has been reported in various cancers and is generally associated with poor survival and prognosis." (PMID 40474968, 2025). "It has been observed that PLAUR is overexpressed in many cancers and is often associated with poor prognoses and survival rates." (PMID 40561678, 2025). "PLAUR encodes a cellular receptor, uPAR, which promotes cancer invasion, metastasis, epithelial–mesenchymal transition (EMT), and resistance to chemotherapy." (PMID 40759369, 2025). "Overexpression of PLAUR has been observed in many cancers and is usually associated with poor survival and prognosis." (PMID 35675366, 2022). "Numerous studies have demonstrated that PLAUR is upregulated in GC and is closely associated with cancer cell invasion and migration 16-18." (PMID 35864968, 2022). "The association of over-activation of PLAUR (uPAR) with increased aggressive carcinoma is also well-studied." (PMID 33593445, 2021). "SERPINE1, along with the identified (overexpressed) DEGs PLAU and PLAUR, is centrally implicated in cancer angiogenesis, while A2M possesses antitumorigenic properties." (PMID 32517019, 2020). "The elevated expression of the gene encoding uPAR (PLAUR) in cancer can be regulated by different mechanisms." (PMID 29484286, 2018). "PLAUR overexpression has been observed in many cancers and is often associated with poor survival and prognosis." (PMID 29254187, 2017). "Such targeting may be essentially cancer cell-specific, as PLAUR expression in healthy tissues is low, and may also cause lesser toxic side-effects." (PMID 27685627, 2016). "Because G2 demonstrated the highest level of PLAUR expression, these data are consistent with our model in which uPAR promotes cancer cell survival under challenging conditions." (PMID 40759369, 2025). "Mining TCGA showed that in PDAC, PLAUR expression is substantially increased and the extent of increase correlates with cancer stage." (PMID 40759369, 2025). "Over-expression of PLAUR within activation of the plasminogen system, has been correlated with poor survival and prognosis in several cancers, in addition to being predictive of adverse cardiovascular events." (PMID 41270070, 2025). "Research has indicated that PLAUR inhibition leads to a reduction in cancer cell growth, invasion, angiogenesis, and metastasis." (PMID 39730379, 2024). "The HIF-dependent upregulation of the urokinase plasminogen activator surface receptor (PLAUR) also increases the proteolytic activity of cancer cells, thereby altering the interaction between integrins and the ECM, promoting cell invasion." (PMID 37490147, 2023). "Urokinase-type plasminogen activator receptor (PLAUR) is involved in a variety of biological processes, including angiogenesis, monocyte migration, cancer metastasis, trophoblast implantation, and wound healing." (PMID 37880277, 2023). "High PLAUR expression was frequently observed in most common cancers and was significantly related to unfavorable outcomes (including OS and DFS) in KIRC." (PMID 36052236, 2022). "PLAU and PLAUR, members of the PLAU system, are overexpressed in several malignant tumors and are associated with the complex phenotype of cancer." (PMID 35141223, 2022). "The abnormal expression of PLAUR is related to the metastasis, invasion, angiogenesis and growth of various cancers, such as pancreatic cancer, breast cancer and glioma." (PMID 35675366, 2022). "The GSCA database was used to examine the role of EME1/HNRNPAB/PLAUR/SEMA3A in 10 cancer pathways and found that EME1 was mainly involved in the activation of apoptosis, cell cycle and DNA damage response and inhibition of RAS/MAPK pathways." (PMID 36091160, 2022).